CFTR (CF transmembrane conductance regulator)
Diseases named in the same sentence as CFTR in open-access papers (continued):
Sharing a sentence is not in itself a finding about the gene and the disease.
colorectal cancer (31 papers, 2012 to 2026). A primary or metastatic malignant neoplasm that affects the colon or rectum. "Beyond CF, as a key regulator of intestinal fluid homeostasis, CFTR, is also implicated in other intestinal disorders including secretory diarrhea, chronic constipation and colorectal cancer (CRC)." (PMID 40066329, 2025). "Another recently published population study found a larger incidence of CFTR mutations in colorectal cancer patients than in the general population." (PMID 37763765, 2023). "This review focuses on the important role of the CFTR ion channel in colorectal cancer in individuals with germline CFTR mutations (both CF patients and carriers) and in sporadic cases of CRC." (PMID 32326161, 2020). "GEO survival analysis was conducted to screen TCF4 target genes associated with the survival of colorectal cancer patients, among which Cystic fibrosis transmembrane conductance regulator (CFTR), Tyrosine-protein kinase Fyn (FYN), and YOD1 deubiquitinase (YOD1) were considered to be eligible." (PMID 37337284, 2023). "Currently, there are several hypotheses that might potentially explain the association of CFTR deficiency with an increased risk of colorectal cancer." (PMID 37175647, 2023). "CFTR dysfunction and deficiency have also been heavily implicated in colorectal cancer (CRC)." (PMID 35626748, 2022). "Dysbiosis resulting from loss of CFTR may promote the production of bacterial taxa that are prevalent in colorectal cancer." (PMID 32326161, 2020). "Disruption of CFTR function and/or dysregulation of CFTR expression have been associated with a wide range of cancers including esophageal, breast, gastric, hepatobiliary, gall bladder, prostate, lung, small intestine and colorectal cancers (CRC)." (PMID 27769067, 2016). "However, it is important to emphasize that there are international studies on the association of CFTR and colorectal cancer, so in future studies, an improved male/female ratio and focus on gastrointestinal tumors, with a previously reported increased ratio in CF, should be aimed for." (PMID 37175647, 2023). "In addition, CFTR deficiency is associated with colorectal cancer." (PMID 36060694, 2022). "Low CFTR expression in colorectal cancer probably results from silencing the CFTR gene by promoter hypermethylation." (PMID 38528462, 2024). "It has been reported that CFTR can be used as a prognostic biomarker of nasopharyngeal carcinoma, colorectal cancer and head and neck cancer." (PMID 35121801, 2022). "In an experiment including 90 patients with colorectal cancer, the disease-free survival at 3 years in the 25% of patients with the lowest CFTR expression was 30% lower than that in patients with a higher CFTR expression." (PMID 36060694, 2022). "We visualized the expression pattern of five (three upregulated and two downregulated) randomly selected differentially expressed representative genes and CFTR, from genes included in the colorectal cancer disease pathway." (PMID 31992345, 2020). "Tezacaftor may have potent anticancer activity against colorectal cancer and improve metastatic processes through its impact on the CFTR gene, consistent with this study." (PMID 38528462, 2024). "It is known that a deficiency in the expression of the CFTR protein is associated with an increased risk of sporadic colorectal cancer, but the mechanism of this effect is not fully resolved." (PMID 37175647, 2023). "Reduced CFTR expression and carrier status for CFTR mutation, even in people without a clinical diagnosis of CF, are recognized as risk factors for colorectal cancer (CRC), cancers of the gallbladder and biliary tract, thyroid cancer, and unspecified NHL." (PMID 37374088, 2023). "The ion channel gene CFTR is a tumor suppressor in colorectal cancer." (PMID 36765944, 2023). "Furthermore, evidence exists that CFTR is a potential tumor suppressor gene for mouse intestinal and human colorectal cancers." (PMID 34274970, 2021).
colorectal cancer (continued). "In summary, consistent with our hypothesis, CFTR modulator drugs such as Tezacaftor, with great promise for performance, may be repurposed for use in treating CFTR-deficient colorectal cancer patients in both CF and non-CF patients." (PMID 38528462, 2024). "In addition, the average age at which colorectal cancer was diagnosed was lower in populations with CFTR mutations than in populations without these mutations (52 years versus 73 years, p 0.01)." (PMID 37763765, 2023). "CFTR mutations or the downregulation of CFTR expression has been strongly implicated in the development and progression of intestinal cancers of both the small and large bowel, particularly colorectal cancer, in patients with CF and patients without CF and in animal models of CFTR-deficiency." (PMID 35743652, 2022). "Notably, drugs targeting CFTR may find application in colorectal cancer." (PMID 38528462, 2024). "In addition, we identified several variants in genes not typically included in relevant gene panels for colorectal cancer, including CFTR, PABPC1 and TYRO3, which may be associated with an increased risk for cancer." (PMID 37296477, 2023). "To conclude, the present study revealed possible involvement of hsa-miR-1246 in early colorectal cancer development and regulation of tumor suppressors AXIN2 and CFTR." (PMID 35216222, 2022).
chronic bronchitis (30 papers, 2012 to 2025). A type of chronic obstructive pulmonary disease characterized by chronic inflammation in the bronchial tree that results in edema, mucus production, obstruction, and reduced airflow to and from the lung alveoli. "The impact of e-cig aerosols on CFTR conductance is particularly relevant given that CFTR dysfunction is associated with chronic bronchitis." (PMID 36225570, 2022). "Considering the acquired loss-of-function CFTR phenotype of HBE in COPD and chronic bronchitis, understanding the molecular basis of acute and extended CS exposure on CFTR inhibition has important therapeutic implications." (PMID 31481727, 2019). "A previous study identified a moderate association between F508del CFTR mutations and in individuals with chronic bronchitis and sweat chloride levels of 60 mmol/L or higher." (PMID 24517344, 2014). "Further, our in vitro and in vivo data provide an explanation for the absence of enhanced susceptibility to cigarette smoke induced chronic bronchitis in individuals heterozygous for CFTR mutations." (PMID 24517344, 2014). "Cigarette smoking has been implicated in the onset of chronic bronchitis through its role in impairing CFTR protein function, posing significantly elevated risks to the people who are genetically predisposed to chronic bronchitis." (PMID 23554779, 2012). "In the present study, we investigated the role of CFTR variations, poly-T, TG-repeats, and M470V in susceptibility to bronchial asthma and chronic bronchitis in a Chinese population in Jiangsu province, China." (PMID 23554779, 2012). "The functional polymorphisms of the CFTR gene and resultant CFTR protein previously demonstrated in healthy Chinese populations was further expanded by observation of bronchial asthma and chronic bronchitis in a specific Chinese population in Jiangsu province." (PMID 23554779, 2012). "CFTR has been implicated in the early development of chronic bronchitis and emphysema." (PMID 25329998, 2014). "To confirm findings in the laboratory, we also investigated whether genetic heterozygosity for CFTR mutations contributes to the prevalence of COPD with chronic bronchitis in cigarette smokers." (PMID 24517344, 2014). "Though CF is one of the most severe manifestations of CFTR gene mutation, other respiratory conditions may also occur, such as bronchial asthma and chronic bronchitis." (PMID 23554779, 2012). "Acquired CFTR deficiency, as asserted by many research groups, may contribute to the physiopathology of cigarette-induced diseases such as chronic bronchitis." (PMID 23554779, 2012). "In an effort to expand the scope of these observations, the present study was to investigate the specific impact of poly-T, TG-repeats, and M470V CFTR variations on susceptibility of a representative Chinese Han population in Jiangsu Province to bronchial asthma and chronic bronchitis." (PMID 23554779, 2012). "Consequently, COPD patients with chronic bronchitis may have a higher rate of CFTR mutations compared to the general population." (PMID 24517344, 2014). "CS exposure induced internalization and insolubility of CFTR and resulted in dehydration of airways surface fluid, which promoted mucus stasis, failure of mucus clearance, and the development of chronic bronchitis." (PMID 36226596, 2023). "First trials verified efficacy of the CFTR potentiator ivacaftor in COPD patients with chronic bronchitis." (PMID 35967318, 2022). "Of note, the patients who were homozygous for the V470 allele carrying the R75Q variant had chronic bronchitis as the dominant symptom of COPD, which suggested a link with CFTR dysfunction." (PMID 34680554, 2021). "Since mucus hypersecretion is a result of neutrophil secretagogue in patients with chronic bronchitis, experimental studies have shown that PDE4s are regulators of the cystic fibrosis transmembrane conductance regulator (CFTR) in human airway epithelial cells." (PMID 34434103, 2021).
chronic bronchitis (continued). "The second source of debate is the role of CFTR dysfunction in the different COPD clinical phenotypes: chronic bronchitis and emphysema." (PMID 34680554, 2021). "Dysfunction in cystic fibrosis transmembrane conductance regulator (CFTR) can be elicited by cigarette smoke and is observed in patients with chronic bronchitis." (PMID 28923049, 2017). "Cigarette smoking is likely to further exacerbate the declining levels of CFTR function, resulting in elevated occurrence of respiratory tract diseases such as chronic bronchitis." (PMID 23554779, 2012). "Noting that once-daily oral administration of roflumilast is indicated for use in patients with COPD and chronic bronchitis, the target population of CFTR modulator therapy in COPD, we evaluated the effect of roflumilast administered to mice by oral gavage over time." (PMID 28923049, 2017). "The mechanistic basis behind the clinical benefits of roflumilast in COPD patients, including its relative predilection for individuals with frequent exacerbations and chronic bronchitis, characteristics potentially attributable to CFTR abnormality, have remained largely undefined." (PMID 28923049, 2017). "Overall, these data indicate that chronic oral roflumilast treatment activates CFTR and reverses acquired CFTR dysfunction in vivo, and may explain its ability to improve health in patients with chronic bronchitis." (PMID 28923049, 2017). "This acquired CFTR dysfunction contributes to inadequate mucociliary transport and is associated with chronic bronchitis and dyspnoea in smokers with and without COPD." (PMID 26066648, 2015). "Five of 127 (3.9%) COPD patients with chronic bronchitis were heterozygous for CFTR mutations which was not significantly different from controls (4.5%) (P = NS)." (PMID 24517344, 2014). "Despite clear evidence that cigarette smoke reduces CFTR mediated anion transport, these results suggest that congenital CFTR mutations do not contribute to a genetic predisposition to the prevalence of COPD and chronic bronchitis." (PMID 24517344, 2014). "This was further supported by the absence of increased CFTR mutation frequency in chronic bronchitis patients when compared to the general population." (PMID 24517344, 2014). "Thus, the presence of the T5-TG12 haplotype of the CFTR gene is likely to play a role in the development and progression of respiratory conditions, such as chronic bronchitis." (PMID 23554779, 2012). "Based on these findings, the phenotypic expression of Tn-TGm-M470V in the CFTR gene may have similar relevance to respiratory conditions, such as chronic bronchitis and bronchial asthma." (PMID 23554779, 2012). "Our study highlights the role of miRNAs as genetic modifiers that may contribute to chronic bronchitis by altering expression of CFTR that regulates lung epithelial surface hydration." (PMID 23226399, 2012). "CFTR mutations do not increase the risk of COPD with chronic bronchitis." (PMID 24517344, 2014). "Due to the important role played by CFTR in the lung, future studies should assess the effect of pharmacological and/or natural compounds that increase/protect CFTR in order to maintain normal lung function and prevent pathologic manifestations that could lead to chronic bronchitis." (PMID 24957904, 2014). "In total, the experimental data indicate why smokers with CFTR mutations may not exhibit a genetic predisposition to develop chronic bronchitis or a gene dose effect, even if chronic bronchitis symptoms are partially mediated by abnormal CFTR function." (PMID 24517344, 2014). "Since smokers with and without COPD exhibit reduced CFTR mediated anion transport, and this is associated with chronic bronchitis, we hypothesized that acquired CFTR dysfunction may also be influenced by the presence of congenital CFTR mutations." (PMID 24517344, 2014).
chronic bronchitis (continued). "The lack of the expected increase in susceptibility to cigarette smoke induced CFTR dysfunction due to the absence of one copy of CFTR prompted us to determine the prevalence of CFTR mutations among COPD patients with chronic bronchitis in comparison to the general Caucasian population." (PMID 24517344, 2014). "However, little is known about whether CFTR expression is affected in COPD patients with a history of smoking but some studies have suggested that it could play a role in chronic bronchitis." (PMID 24957904, 2014). "Thus, it has been hypothesized that cigarette smoke-induced CFTR dysfunction contributes to the development of chronic bronchitis." (PMID 24957904, 2014). "Reduced CFTR activity measured by NPD was also associated with the severity of bronchitic symptoms (r = 0.30, P<0.05), as assessed by BCSS, even when controlled for cigarette smoking (r = 0.31, P<0.05), indicating an association with a phenotype reminiscent of CF (i.e. chronic bronchitis)." (PMID 22768130, 2012). "Although clinical trials of CFTR-enhancing drugs in COPD patients are in the early stages, a recent study shows that ivacaftor in patients with chronic bronchitis leads to an improvement in symptoms and chlorine levels in the sweat test." (PMID 34680554, 2021). "To enrich the population for those likely to exhibit CFTR abnormality, and assure best matching with our control group, we restricted the analysis to individuals with COPD, chronic bronchitis and of Caucasian descent." (PMID 24517344, 2014). "However, recent findings suggest that CFTR modulators, such as Ivacaftor (a CFTR enhancer), show promise in treating acquired CFTR dysfunction in COPD patients, particularly those with chronic bronchitis." (PMID 39458647, 2024). "A study comparing healthy non-smokers with current smokers, with and without COPD, showed a significant reduction in CFTR activity with correlations of this activity with the presence of chronic bronchitis and dyspnoea scores." (PMID 34680554, 2021). "We found that CFTR mutations are not more frequent in COPD patients with moderate to severe obstruction and chronic bronchitis symptoms compared to a control population of Caucasian individuals." (PMID 24517344, 2014). "The frequency of CFTR mutations among those with COPD and chronic bronchitis was no different than the mutation rate seen in the control population (1356 of 32900, 4.1%; P = NS)." (PMID 24517344, 2014). "Since, our analyses were focused on one sub-phenotype of COPD (i.e. chronic bronchitis), it would be beneficial to conduct additional CFTR genetic analysis in a larger cohort of subjects to rule out CFTR as a contributor." (PMID 24517344, 2014). "It has been reported that cigarette smoke exposure, the major cause of COPD, leads to downregulation of CFTR mRNA, protein and function and CFTR activity is reduced in smokers both with and without COPD associated with chronic bronchitis and the severity of dyspnea." (PMID 35392868, 2022). "Taken together, our results highlight the importance of not only CFTR but also BK channel function in maintaining ASL homeostasis and emphasize the possibility that pirfenidone could be employed as a novel therapeutic regimen to help improve MCC in smoking-related chronic bronchitis." (PMID 28874823, 2017).